SEC14L6 (SEC14 like lipid binding 6)
Tractability: PROTAC: ubiquitination databases record sites on it.
Gene: Protein-coding gene on chromosome 22 (30,522,799 to 30,546,741, reverse strand). Ensembl gene ENSG00000214491.
Subcellular location (Human Protein Atlas): Nucleoplasm
Gene Ontology:
Cellular component: cytoplasm
Genetic constraint (gnomAD): Loss-of-function variants: 37 observed, 46.36 expected, observed/expected ratio (o/e) 0.8, 90% interval 0.61 to 1.05. The upper end of that interval is the gene's LOEUF score, 1.05, which puts it in group 4 of 6, group 1 being the genes least tolerant of losing a copy. Missense variants: 423 observed, 443.31 expected, observed/expected ratio (o/e) 0.95, 90% interval 0.88 to 1.03. Synonymous variants: 155 observed, 174.74 expected, observed/expected ratio (o/e) 0.89, 90% interval 0.78 to 1.01.
Homologues: Orthologues: chimpanzee SEC14L6 (97% identical), zebrafish sec14l8 (57% identical), zebrafish sec14l7 (54% identical), Drosophila melanogaster CG13893 (29% identical), Caenorhabditis elegans T23G5.2 (28% identical), Caenorhabditis elegans ctg-1 (26% identical), Drosophila melanogaster retm (25% identical), Caenorhabditis elegans F28H7.8 (23% identical), Caenorhabditis elegans C34C12.6 (20% identical). Paralogues in human: SEC14L4 (78% identical), SEC14L3 (68% identical), SEC14L2 (67% identical), SEC14L1 (31% identical), SEC14L5 (31% identical), TTPA (16% identical).